PDGFA (platelet derived growth factor subunit A)
Diseases named in the same sentence as PDGFA in open-access papers (continued):
Sharing a sentence is not in itself a finding about the gene and the disease.
breast carcinoma (24 papers, 2005 to 2025). "In breast cancer, PDGFa overexpression has been linked to metastasis, tumor aggressiveness, and progression." (PMID 38969706, 2024). "In addition, expression of PDGFA has been shown to be associated with high vascular density, lymph node metastasis and tumor recurrence in breast cancer." (PMID 27029061, 2016). "The positive correlation between PDGFA expression and N stage was observed in gastric carcinoma, breast cancer, and oral squamous cell carcinoma, suggesting that PDGFA was a possible accelerator for lymph node metastasis." (PMID 34011067, 2021). "Other literature shows platelet-derived growth factor subunit a (PDGFA) is a transcription target of FoxM1, and FoxM1 promotes breast cancer tumorigenesis by transcriptionally activating PDGFA, which led to further Akt phosphorylation in breast cancer cells." (PMID 31253784, 2019). "Recently, PDGFA has been proved to play important roles in breast cancer, but whether PDGFA serve as important factor in bladder cancer development has not been evidenced." (PMID 26544730, 2015). "Interestingly, overexpression of PDGFR-α expression in breast cancer has previously been associated with lymph node metastasis (P = 0.0079) in a cohort of 181 invasive ductal breast carcinomas patients suggesting that PDGFA may be clinically relevant for breast cancer lymph node metastasis." (PMID 23118918, 2012). "Histone lactylation (e.g., H3K18la) drives pro-tumorigenic gene programs, such as PDGFA upregulation in macrophages and ZFP64-mediated chemoresistance in breast cancer." (PMID 40565047, 2025). "The mRNA expression levels for eight pro-angiogenic genes [VEGFA, HGF, FGF1, FGF2, ANGPT1, ANGPT2, PDGFA, and PDGFB] were obtained from the METABRIC (Molecular Taxonomy of Breast Cancer International Consortium) dataset available at cBioPortal public domain." (PMID 39302921, 2024). "To rule out the cell line-specific effect, we inhibited KDM2A in SkBr3 breast cancer cells and found the expression of JAG1 and PDGFA was also reduced." (PMID 27029061, 2016). "UTI and TXT down-regulate the expression of mRNA and protein of IGF-1R, PDGFA, NGF, NF-κB, and JNk-2 in breast cancer cells and xenografted breast tumors." (PMID 22217202, 2012). "In the present experiment, we find that UTI and TXT inhibit gene and protein expression of IGF-1R, PDGFA, NGF, NF-κB, and JNk-2 in breast carcinoma cells and the effect of UTI+TXT is strongest." (PMID 22217202, 2012). "The gene expression and protein expression of IGF-1R, PDGFA, NGF, NF-κB and JNk-2 in breast cancer cells was inhibited by UTI and TXT." (PMID 22217202, 2012). "After being respectively treated with UTI, TXT and UTI+TXT for 48h, the gene expression of IGF-1R, PDGFA, NGF, NF-κB, and JNK2 in human breast cancer cells decreased significantly compared with the control group (P < 0.05) in the order of UTI+TXT > TXT > UTI > control." (PMID 22217202, 2012). "Western blotting showed that after primary breast carcinoma cells were respectively treated with UTI, TXT, and UTI+TXT for 48 h, the protein expression of IGF-1R and PDGFA decreased significantly compared with the control group (P < 0.05) in the order of UTI+TXT > TXT > UTI." (PMID 22217202, 2012). "The overexpression of miR-20a in MCF7 breast cancer cells did not change the mRNA expression of VEGFA (p = 0.20) or other angiogenic factors, such as PDGFA (p = 0.83) or CTGF (p = 0.83)." (PMID 29617404, 2018).
glioblastoma (16 papers, 2004 to 2025). The most malignant astrocytic tumor (WHO grade IV). "Furthermore, single-cell RNA sequencing (scRNA-seq) has provided crucial insights into the transcriptomic heterogeneity of glioblastomas, identifying key genes such as PDGFA, PDGFRA, CREB1, and PLAT that are strongly linked to tumor progression and patient survival." (PMID 40332008, 2025). "We thus propose a model of signaling pathways in the STAT3/CEBPD/PDGFA axis mediating inflammatory factor-induced stemness in glioblastoma." (PMID 31300060, 2019). "PDGFR inhibition in GBM cell lines universally triggers a G2/M arrest and in a PDGFRA/PDGFA driven glioblastoma mouse model chronic activation of PDGFRA facilitates microtubule dynamics during mitosis, suggesting a role for PDGFR in driving GBM cells towards mitosis." (PMID 33478100, 2021). "PDGFA promotes proliferation and self-renewal in glioblastoma stem cells." (PMID 29212247, 2017). "Platelet-derived growth subunit A (PDGFA) plays critical roles in development of glioblastoma (GBM) with substantial evidence from TCGA database analyses and in vivo mouse models." (PMID 35105853, 2022). "In another study, freshly resected glioblastoma multiforme cells were grown in a special serum-free medium supplemented with EGF and FGF-2 or PDGFA alone." (PMID 38392188, 2024). "This inconsistency has to be investigated in more detail, since LuzP6 is coded for on chromosome 7, which can show gains in glioblastoma and carries coding regions for EGFR and PDGFA." (PMID 31006040, 2019). "We analysed gene expression of the PDGF system (PDGFA, PDGFB, PDGFC, PDGFD, PDGFRA, PDGFRB) in 36 GBMs studied on Ivy Glioblastoma Atlas Project." (PMID 29127351, 2017). "The classical subgroup of glioblastoma, as defined by TCGA, was found to have high expression of EGFR and PDGFA." (PMID 21934682, 2011). "Therefore, we concluded that KDELC2 promotes glioblastoma angiogenesis by upregulating ZEB2, VEGF-A, VEGF-R1, and PDGFA expression." (PMID 37107298, 2023). "When the presence or absence of PDGFA/PDGFRA overexpression (+++) was defined according to histological type, a trend for PDGFA and PDGFRA coexpression in glioblastomas was found (P=0.069)." (PMID 19707201, 2009).
prostate carcinoma (13 papers, 2007 to 2025). A carcinoma that arises from epithelial cells of the prostate gland. "Gene ontology analysis of differentially expressed genes revealed that lack of Sost in the bone microenvironment up-regulated several genes associated with the GO term “chemotaxis” including MET, PDGFA, FER, NRP2, and EZR in prostate cancer." (PMID 27600237, 2015). "miR - 135b, significantly downregulated in prostate cancer, promotes bone metastasis by enhancing the migration capacity of prostate cancer cells, with PLAG1, JAKMIP2, PDGFA, and VTI1B identified as potential mediators." (PMID 40837012, 2025). "In prostate cancer, EGR1 could upregulate angiogenic and osteoclastogenic factors, including PDGFA, IL6, IL8, etc. and thus promote cancer metastasis." (PMID 36932397, 2023).
atherosclerosis (8 papers, 2016 to 2024). A disease characterized by the build-up of fatty material and calcium deposition in the arterial wall resulting in partial or complete occlusion of the arterial lumen. "Patients with STEMI had higher secretoglobin family 3A member 2 and tartrate-resistant acid phosphate type 5 and lower platelet-derived growth factor subunit A, which are proteins associated with atherosclerosis severity and plaque development mediated via altered phospholipid metabolism." (PMID 33396480, 2020). "CORIN is a serine protease mainly expressed in the heart that plays an important role in the development of atherosclerosis, and PDGFA is an growth factor involves in cholesterol-induced atherosclerosis." (PMID 39758846, 2024).
liver fibrosis (7 papers, 2019 to 2025). "Increased expression of PDGFA was observed to correlate with hepatic fibrosis risk, hyperinsulineamia and insulin resistance, with levels of CpG methylation at this loci also having an inverse correlation with PDGFA expression." (PMID 40356723, 2025). "Transgenic mouse strains overexpressing PDGFA, -B, -C or -D all develop liver fibrosis." (PMID 35454853, 2022). "Few studies on the relationship between PDGFA and BA hepatic fibrosis have been reported." (PMID 32662506, 2020). "Additionally, PDGFA expression is positively correlated with hepatic fibrosis and NASH risk, and as such, the over-expression of PDGF-AA in mouse liver results in spontaneous liver fibrosis." (PMID 33193730, 2020). "Platelet-derived growth factor subunit A (PDGFA), as one of participants in liver fibrosis, the overexpression of PDGFA through DNA hypomethylation may lead to the development of BA, but the pathogenesis is still unclear." (PMID 32662506, 2020).
gastric cancer (6 papers, 2012 to 2023). A primary or metastatic malignant neoplasm involving the stomach. "In human gastric cancers, high levels of PDGFA correlate with high-grade carcinomas and reduced patient survival." (PMID 33524869, 2021).
melanoma (6 papers, 2020 to 2025). A malignant, usually aggressive tumor composed of atypical, neoplastic melanocytes. "In this work, we observed that the overall survival outcome was significantly associated with a high level of PDGFA and a low level of KLK6 and KLK10 expression in melanoma tumors and that these genes were expressed in an opposite way in XP patients who developed melanoma at a young age." (PMID 35974070, 2022). "However, high or low expression of ANGPT1, PDGFA, and FGF2 has no impact on the survival probability of patients with primary melanoma." (PMID 34102002, 2021).
ovarian carcinoma (6 papers, 2019 to 2024). A malignant neoplasm originating from the surface ovarian epithelium. "Recent studies have explored the inflammatory expression signatures in ovarian cancers, in which elevated expression of intratumoral PDGFA was found to increase the risk of death and correlate with adverse outcomes." (PMID 32962103, 2020). "Here, it is shown that the adrenergic regulation of macrophages and PDGFA might play a role in ovarian cancer progression." (PMID 32962103, 2020). "Furthermore, in ovarian cancer patients, high PDGFA expression correlated with worse outcomes." (PMID 32962103, 2020). "The results showed a higher expression of PDGFA and PDGFB in ovarian cancer related to a poorer clinical survival (worse OS and PPS for PDGFA, worse PPS for PDGFB)." (PMID 36199822, 2022). "Intriguingly, the expression levels of PDGF ligands in tumor cells were inconsistent, as PDGFA and PDGFB stained strongly, whereas PDGFC and PDGFD stained weakly in ovarian cancer tumor cells." (PMID 36199822, 2022). "In ovarian cancer, PDGFB (P < 0.05), PDGFD (P < 0.05), PDGFRA (P < 0.001), and PDGFRB (P < 0.001) had a significant positive correlation with macrophage M2 infiltration, and PDGFA had a negative association with macrophage M1 infiltration (P < 0.01)." (PMID 36199822, 2022). "The results showed that high PDGFA (Affymetrix ID: 205463_s_at) expression correlated with decreased overall survival (OS) but did not impact progression-free survival (PFS) in ovarian cancer patients (HR 1.54 (95% CI 1.19–1.99); p < 0.001 for OS; HR 0.87 (95% CI 0.68–1.11); p < 0.25 for PFS)." (PMID 32962103, 2020). "However, there were no apparent differences in the protein expression of PDGFA and PDGFC in tumor tissues of ovarian cancer and normal ovarian tissues." (PMID 36199822, 2022).
pancreatic cancer (6 papers, 2017 to 2025). "Mucin 1 (MUC1), a transmembrane mucin glycoprotein, regulates PDGFA expression and secretion in pancreatic cancer cells, accordingly, influences the proliferation of pancreatic tumors." (PMID 34858977, 2021). "These genes are the major components regulating the glucose metabolism and proteolysis in pancreatic cells, indicative of poor prognosis and involved in PDGFA expression in pancreatic cancer progression, respectively." (PMID 31336658, 2019).
bladder cancer (5 papers, 2014 to 2024). "Thus further study may be needed to uncover the roles of PDGFA in KLF5-regulated angiogenesis in bladder cancer." (PMID 26544730, 2015). "Some cancer-associated DSGs in our result were reported in the other cancers but not reported in the bladder cancer yet, such as PDGFA, MACF1, ADD3 and NUMB." (PMID 24622401, 2014).
colorectal cancer (5 papers, 2012 to 2025). A primary or metastatic malignant neoplasm that affects the colon or rectum. "PHF20L1 promotes EMT of colorectal cancer cells and increases their invasiveness and metastatic abilities; it also regulates the expression of various angiogenic factors (such as ANGPT2, FGF1, PDGFA, and VEGFA) and promotes angiogenesis in colorectal cancer tissues." (PMID 40723918, 2025).
COVID-19 (5 papers, 2022 to 2023). A disease caused by infection with severe acute respiratory syndrome coronavirus 2. "Expressions of the angiogenic factors VEGF and PDGFA and small vessel volumetric proportion (CD31+) increased in the testis of COVID-19 patients." (PMID 36797789, 2023). "Non-severe COVID-19 was distinguished from other disease conditions in both children and adults by expression of PDGFA, AMFR, and FGF23, markers that have been observed to be upregulated in prior studies of acute COVID-19 infection." (PMID 37638019, 2023). "Additionally, IL-4, IL-12, IL-2, CXCL10, platelet derived growth factor subunit A (PDGFA), and IFN-α2a kinetic changes were similar between the natural course of early COVID-19 and inhaled budesonide." (PMID 35397798, 2022).
lymph node metastasis (5 papers, 2012 to 2024). "PDGFA expression was inversely correlated with the age of the patient, lymph node metastasis, and the NPI." (PMID 39302921, 2024). "We found positive correlations of the mRNA levels of PDGFA, PDGFB, and PDGFRB with lymph node metastasis and poor overall survival (OS)." (PMID 32235327, 2020). "The elevated mRNA levels of PDGFA and PDGFB correlated significantly with lymph node metastasis (p = 0.002 and p = 0.011, respectively)." (PMID 32235327, 2020).
myocardial infarction (5 papers, 2017 to 2024). Gross necrosis of the myocardium, as a result of interruption of the blood supply to the area, as in coronary thrombosis. "In addition, results of an animal study showed that mRNA expressions of PDGFA, PDGFB, PDGFC, PDGFD and PDGFRs exhibited different changes in the infarcted rat heart in the early and late stages after myocardial infarction." (PMID 39569832, 2024). "They found that the expression of PDGFA, PDGFD and PDGFRB in the infarcted myocardium were increased after myocardial infarction, whereas PDGFB and PDGFC mRNAs were reduced and protein levels at infarcted myocardium were all significantly reduced in the early stage of myocardial infarction." (PMID 39569832, 2024).
breast tumor (4 papers, 2012 to 2024). "Both PDGFA and PDGFB were expressed in breast tumor samples in this study and their mRNA transcript levels were positively correlated." (PMID 39302921, 2024).
hepatocellular carcinoma (4 papers, 2016 to 2023). A malignant tumor that arises from hepatocytes. "Irradiation significantly upregulated the mRNA expressions of FasL, TRAIL, TNF-α, and TGF-β1 in hepatoma cells, and downregulated the mRNA expressions of IGF-1 and PDGFB, but no obvious effects on the expressions of VEGFA, PDGFA, and IL-6." (PMID 27431384, 2016).
lung adenocarcinoma (4 papers, 2020 to 2024). A carcinoma that arises from the lung and is characterized by the presence of malignant glandular epithelial cells. "For example, PDGF (Platelet-derived growth factor subunit A) has been shown to be involved in recruitment and activation of cancer-associated fibroblasts in lung adenocarcinoma and to also exert similar effect on pancreatic stellate cells and fibroblasts in PDAC tumors." (PMID 32370304, 2020). "WNT10A, PDGFA, TNF, and NRG1 had been identified as important paracrine factors from infiltrated dendritic cells to regulate neuropathic pain associated with lung adenocarcinoma." (PMID 32434423, 2020). "TNF, WNT10A, PDGFA, and NRG1 derived from infiltrated dendritic cells in lung adenocarcinoma microenvironment were proved to worsen neuropathic pain associated with cancers by sensitizing sensory neurons." (PMID 32434423, 2020).
pancreatic ductal adenocarcinoma (4 papers, 2021 to 2024). An infiltrating adenocarcinoma that arises from the epithelial cells of the pancreas. "PDGFA has been found to have a pivotal regulatory function in several cancers, such as head and neck squamous cell carcinoma, pancreatic ductal adenocarcinoma, and papillary thyroid carcinoma." (PMID 37686118, 2023). "PDGFA is one of the drivers of tumor growth, angiogenesis, and metastasis formation in Pancreatic Ductal Adenocarcinoma (PDA), and hence its downregulation plausibly contributes to the synergy observed." (PMID 34585118, 2021). "A recent study showed that combined treatment of a MAPK inhibitor (Trametinib) and Palbociclib induced senescence and these senescent pancreatic ductal adenocarcinoma cells showed increased secretion of pro‐angiogenic factors (VEGF, PDGFA/B, and FGF2) and MMPs (MMP2/3/7/9/10)." (PMID 37854019, 2024).
Brain tumors (3 papers, 2017 to 2018).
cholangiocarcinoma (3 papers, 2013 to 2021). A carcinoma that arises from the intrahepatic biliary tree (intrahepatic cholangiocarcinoma) or from the junction, or adjacent to the junction, of the right and left hepatic ducts (hilar cholangiocarcinoma). "We determined the gene expressions of FLT1, FLT4, HPSE, Hif1a, HB-EGF, PDGFA, PDGF-RA and EGFR in FFPE samples of patients with cholangiocarcinoma." (PMID 23704979, 2013).
colon carcinoma (3 papers, 2016 to 2021). "In colon carcinoma, ANGPT2 and VEGF‐A expression is significantly higher (P < 0.0001) in the tumor compared to the adjacent normal colon, whereas expression of ANGP1, PDGFA, and FGF2 is significantly lower (P < 0.0001)." (PMID 34102002, 2021). "In patients with colon carcinoma (n = 262), high ANGP2 and VEGF‐A expression, individually, predicts a somewhat worse probability of survival compared to low ANGPT2 or VEGF‐A expression, whereas high or low ANGPT1, PDGFA, and FGF2 expression has no impact." (PMID 34102002, 2021).
esophageal cancer (3 papers, 2013 to 2025). A primary or metastatic malignant neoplasm involving the esophagus. "A gene expression analysis found PDGFA to have significantly higher expression levels in esophageal cancer tissues compared to corresponding normal samples." (PMID 39796775, 2025).
esophageal squamous cell carcinoma (3 papers, 2021 to 2025). Esophageal squamous cell carcinoma (ESCC) is a type of esophageal carcinoma (EC) that can affect any part of the esophagus, but is usually located in the upper or middle third. "High expression of PDGFA has been reported to predict a poor prognosis in esophageal squamous cell carcinoma." (PMID 38111825, 2023). "High expression of PDGFA predicts poor prognosis of esophageal squamous cell carcinoma." (PMID 39796775, 2025). "However, PDGFA expression and its clinical significance in esophageal squamous cell carcinoma (ESCC) are not clear." (PMID 34011067, 2021).
gliosarcoma (3 papers, 2009 to 2021). A rare histological variant of glioblastoma (WHO grade IV) characterized by a biphasic tissue pattern with alternating areas displaying glial and mesenchymal differentiation (WHO). "The different expression of long isoforms of PDGFA was also reported in gliosarcomas of mouse and liver cancer of rat." (PMID 24622401, 2014). "We have previously shown that 100% of gliosarcomas express PDGFA." (PMID 19707201, 2009).